CALCOCO2 (calcium binding and coiled-coil domain 2)
Description:
Xenophagy-specific receptor required for autophagy-mediated intracellular bacteria degradation. Acts as an effector protein of galectin-sensed membrane damage that restricts the proliferation of infecting pathogens such as Salmonella typhimurium upon entry into the cytosol by targeting LGALS8-associated bacteria for autophagy. Initially orchestrates bacteria targeting to autophagosomes and subsequently ensures pathogen degradation by regulating pathogen-containing autophagosome maturation. Bacteria targeting to autophagosomes relies on its interaction with MAP1LC3A, MAP1LC3B and/or GABARAPL2, whereas regulation of pathogen-containing autophagosome maturation requires the interaction with MAP3LC3C. May play a role in ruffle formation and actin cytoskeleton organization and seems to negatively regulate constitutive secretion.
Synonyms: NDP52; MGC17318
Tractability: Small molecule: a structure with a bound ligand is known. Antibody: UniProt places it where antibodies can reach, with high confidence. PROTAC: ubiquitination databases record sites on it; its protein half-life has been measured.
Gene: Protein-coding gene on chromosome 17 (48,830,971 to 48,868,228, forward strand). Ensembl gene ENSG00000136436.
Subcellular location: Cytoplasm, perinuclear region; Cytoplasm, cytoskeleton; Cytoplasmic vesicle, autophagosome membrane
Subcellular location (Human Protein Atlas): Cytosol; Vesicles
Gene Ontology:
Molecular function: protein binding; protein homodimerization activity
Biological process: positive regulation of autophagosome maturation; response to type II interferon; xenophagy; viral process
Cellular component: autophagosome; cytoplasm; cytosol; membrane; perinuclear region of cytoplasm; PML body; nucleus; autophagosome membrane; cytoskeleton
Genetic constraint (gnomAD): Loss-of-function variants: 18 observed, 28.59 expected, observed/expected ratio (o/e) 0.63, 90% interval 0.43 to 0.93. The upper end of that interval is the gene's LOEUF score, 0.93, which puts it in group 3 of 6, group 1 being the genes least tolerant of losing a copy. Missense variants: 230 observed, 278.4 expected, observed/expected ratio (o/e) 0.83, 90% interval 0.74 to 0.92. Synonymous variants: 89 observed, 92.77 expected, observed/expected ratio (o/e) 0.96, 90% interval 0.81 to 1.14.
Homologues: Orthologues: chimpanzee CALCOCO2 (99% identical), macaque CALCOCO2 (95% identical), dog CALCOCO2 (84% identical), pig CALCOCO2 (84% identical), rabbit CALCOCO2 (76% identical), guinea pig CALCOCO2 (63% identical), tropical clawed frog calcoco2 (33% identical), mouse Calcoco2 (30% identical), zebrafish calcoco2 (23% identical). Paralogues in human: TAX1BP1 (31% identical), CALCOCO1 (28% identical).
Diseases named in the same sentence as CALCOCO2 in open-access papers:
CALCOCO2 is named in the same sentence as 44 diseases in open-access papers, as found by Europe PMC text mining. Sharing a sentence is not in itself a finding about the gene and the disease. The quoted sentences say what the papers report.
viral infection (12 papers, 2017 to 2025). "For viral infection, it was previously reported that CALCOCO2 binds the non-structural protein 2 of Chikungunya virus to promote viral replication in humans but not mice, suggesting not only a proviral function but also a species-specific role for CALCOCO2." (PMID 30154446, 2019).
Crohn disease (5 papers, 2018 to 2025). A gastrointestinal disorder characterized by chronic inflammation involving all layers of the intestinal wall, noncaseating granulomas affecting the intestinal wall and regional lymph nodes, and transmural fibrosis. "In addition, two of the top dysregulated ALP genes, TIAL1 and CALCOCO2, have been implicated as key factors in ulcerative colitis- and Crohn’s disease-related inflammation, respectively." (PMID 34446734, 2021).
lung carcinoma (2 papers, 2012 to 2022). "CALCOCO2 is an autophagy receptor that contributes to autophagy addiction in Ras-driven lung cancer." (PMID 35768804, 2022).
allergic asthma (1 paper, 2022). A asthma with a basis in a pathological type I hypersensitivity reaction. "In addition, RNA-seq analysis suggests that autophagy is one of the major pathways and that CALCOCO2/NDP52 and S1009 are major autophagy-associated genes in AT2 cells that may contribute to the AhR-mediated cockroach allergen–induced airway inflammation and, subsequently, allergic asthma." (PMID 35935956, 2022).
asthma (1 paper, 2022). "Further analysis demonstrated an increased expression of Calcoco2 in the lung tissues of our asthma mouse model as assessed by immunostaining." (PMID 35935956, 2022). "Our study demonstrated that Calcoco2 was highly expressed in the lung tissues and AT2 cells of our asthma mouse model as determined by immunofluorescence staining." (PMID 35935956, 2022).
degenerative joint disease (1 paper, 2023). "The CALCOCO2 and NXPH3 genes, which are involved in degenerative joint disease in humans, have been discovered in a Soviet heavyweight at ECA11." (PMID 37510415, 2023).
germ cell tumours (1 paper, 2023). "Further examination of the genes that were lower than expected revealed six FGFRi-MEKi DEGs associated with stem cell differentiation, cell self-renewal, cancer, cell proliferation and survival and germ cell tumours, including Etv1 and Etv4, Pdk1, Ret, Tdgf1 and Calcoco2." (PMID 38053127, 2023).
lung squamous cell carcinoma (1 paper, 2023). "TMEM120B, HMOX2, CALCOCO2, LONP2, ZNF440, CLCC1, and CHMP3 were identified to be optimal prognostic factors for lung squamous cell carcinoma (LUSC)." (PMID 36999050, 2023).
schizophrenia (1 paper, 2022). A major psychotic disorder characterized by abnormalities in the perception or expression of reality. "In two probands of these 14 families, we detected rare TREs in three genic regions (CALCOCO2 and FXN in one family, and SHANK1 in the other family) that were also identified in our primary schizophrenia cohort." (PMID 35546631, 2022).
infection (36 papers, 2013 to 2025). The state of being infected such as from the introduction of a foreign agent such as serum, vaccine, antigenic substance or organism. "Intriguingly, relative mRNA levels of both NBR1 and CALCOCO2 (NDP52) significantly increased at the late infection time point, specifically at 18 hpi." (PMID 39120287, 2024). "Gene knockout of NDP52/Calcoco2 and interference with the protein ubiquitination of IRF3 by a mutation on K313 (K313) diminished the PSMD14-enhanced SeV-infection-triggered IFN response." (PMID 36980296, 2023). "Intriguingly, it was discovered that the cleavage fragment generated during infection retains the pro-viral function of full-length CALCOCO2/NDP52." (PMID 30475087, 2019). "The authors speculate that T6BP/TAX1BP1 and CALCOCO2/NDP52 could target substrates to autophagosomes whose degradation is required for MeV replication to occur, such as infection-induced apoptotic factors." (PMID 34167456, 2021). "We report that in addition to NDP52/CALCOCO2 and OPTINEURIN/OPTN, another autophagy receptor, namely T6BP/TAXIBP1, also regulates the maturation of autophagosomes by promoting their fusion with lysosomes, independently of any infection." (PMID 28531150, 2017).
cancer (5 papers, 2019 to 2023). A tumor composed of atypical neoplastic, often pleomorphic cells that invade other tissues. "Other genes, such as CALCOCO2, RCAN2, ADI1, ECHS1, PLOD1 and VTI1B were associated with tumorigenesis or angiogenesis in some other cancers 33-35." (PMID 31632497, 2019). "SNF8, UBE2Z, CALCOCO2, and ATP5MC1 have been shown a core function in metabolic disease and cancer." (PMID 35052342, 2021).
tumor (4 papers, 2017 to 2024). "On the other hand, as a protein closely associated with autophagy, CALCOCO2 might regulate the extent of autophagy in tumor cells under certain circumstances." (PMID 38463514, 2024).
CALCOCO2 also shares sentences with these, for which no sentence is quoted: bacterial infection (6 papers); myocardial infarction (3); Salmonella Infections (3); Alzheimer disease (2); cervical cancer (2); non-small cell lung carcinoma (2); osteosarcoma (2); amyotrophic lateral sclerosis (1); cardiovascular diseases (1); chronic hepatitis B (1); co-infection (1); colorectal cancer (1); COVID-19 (1); diabetes (1); dilated cardiomyopathy (1); heart failure (1); hepatitis B virus infection (1); Insulin resistance (1); liposarcoma (1); Listeria Infections (1); metabolic disease (1); multiple sclerosis (1); myocardial ischemia (1); pancreatic adenocarcinoma (1); parasitemia (1); psoriasis (1); Sepsis (1); Stroke (1); tauopathies (1); type 2 diabetes (1).
A further 2 diseases each share a sentence with CALCOCO2 in 1 paper.